IL6 (interleukin 6)
Diseases named in the same sentence as IL6 in open-access papers (continued):
Sharing a sentence is not in itself a finding about the gene and the disease.
lung carcinoma (continued). "The study revealed that PTH, CRP, IL-6, and lipid profile parameters play a significant role as markers of lung cancer progression." (PMID 39816276, 2024). "Over the list of cytokines, IL-6 and IL-17 tend to hype inflammatory responses and remodel lung cancer pathogenesis through immunological defense mechanisms." (PMID 38279220, 2024). "Conversely, WA lung cancer patients demonstrated significantly elevated levels of IL-6 compared to their controls (p = 0.017)." (PMID 38276239, 2024). "The IL-6 secreted by metastatic lung cancers enhances osteoclastogenesis, leading to osteolytic bone metastasis." (PMID 38993553, 2024). "Conversely, WA lung cancer patients exhibited significantly elevated levels of IL-6 compared to controls." (PMID 38276239, 2024). "Lung cancer cells secrete IL-6 and IL-11, which can activate various signaling pathways such as PI3K/Akt and MAPK, promoting cell proliferation and migration." (PMID 38571500, 2024). "The results of this in vivo experiment suggested that TAMs promoted the EMT pathway in LUAD cells and promoted lung cancer progression through the secretion of IL-6." (PMID 38424624, 2024). "Inflammatory IL-6 and IL-17 secreted by lung cancer cells in response to HPV stimuli would significantly exacerbate the condition of microenvironmental inflammation and lead to lung tumorigenesis and tumor development." (PMID 38542056, 2024). "Evidences show that the expression of IL6 is significantly higher in NSCLC tissues, and a high expression level of IL6 exhibits the potential to predict the occurrence and metastasis of lung cancer." (PMID 39152779, 2024). "First, IL-6 controls cigarette smoke-induced lung cancer migration, as demonstrated with IL-6 shRNA blocking cell migration of A549B[α]P and A549CSE." (PMID 38993553, 2024). "Through the reconstructed model, we illustrated that the crosstalk between immune cells in the lung cancer model is a result of the IL-6/IL-17 signaling axis that is activated upon the recognition of tumor antigens by lung cancer cells." (PMID 38279220, 2024). "Different studies on lung cancer found that the inflammatory mediators were overexpressed, especially IL-6." (PMID 38474590, 2024). "LDOC1 interacts with Ligand-of-Numb protein X1 (LNX1), an E3 ligase, to induce Janus kinase 2 (JAK2) ubiquitination and degradation, which negatively regulates STAT3 activation and IL-6 secretion in lung cancer cells." (PMID 39682774, 2024). "In lung cancer, IL-6 during the initial stages worked to generate an anti-tumor effect along with other cytokines that were secreted in the tumor microenvironment." (PMID 38279220, 2024). "We noted that high levels of IL-6 in lung cancer cells exposed to CSE and B[α]P stimulated IL-6, promoting osteoclastogenesis." (PMID 38993553, 2024). "In lung cancer, IL-6 is activated through different signaling mechanisms that work in a context-dependent manner." (PMID 38279220, 2024). "Research shows that the dysregulation of the IL-6/STAT3 signaling pathway mediates lung cancer cell proliferation and invasion, and the suppression of the IL-6/STAT3 pathway prevents the progression of lung cancer." (PMID 39258670, 2024). "Released IL-6 can induce the EMT pathway in lung cancer to enhance migration, invasion, and metastasis." (PMID 38424624, 2024). "The primary objective of this study was to evaluate and compare the serum levels of PTH, CRP, lipid profile parameters, and IL-6 across different stages of lung cancer." (PMID 39816276, 2024). "For example, CAFs have been proven to secrete many cytokines or growth factors, such as IL‐6, periostin, hepatocyte growth factors, and insulin‐like growth factors, mediating an osimertinib‐resistant phenotype in lung cancer cells." (PMID 39036343, 2024). "M.tb-induced TNF-α and IL-6 promote the expression of antiapoptotic genes through the NF-κB pathway, which further contributes to the development of lung cancer." (PMID 38542056, 2024).
lung carcinoma (continued). "Such a mechanisms appears to take place in lung cancer, where conditioned medium from Lewis lung cancer cells was shown to drive M2 polarization and IL-6 production in PBMCs." (PMID 38422751, 2024). "In contrast, TAM-induced lung cancer metastases were greatly reduced when neutralizing antibodies against IL-6 were uesd." (PMID 38424624, 2024). "By releasing chemokine receptors including CXCR3/4 and CCR5/7, and secreting pro-inflammatory cytokines, notably IL-6, TANs play a pivotal role in the pathogenesis of lung cancer." (PMID 38339264, 2024). "In conclusion, our results disclose that cigarette smoking promotes IL-6-dependent lung cancer migration through PI3K, Akt and NF-κB signaling pathways." (PMID 38993553, 2024). "Numerous studies have shown that IL-6 is overexpressed not only in cancerous tissues but also in the sera of patients with different malignancies, such as lung cancer, multiple myeloma, leukemia, gastric cancer, and colon cancer." (PMID 38529301, 2024). "In this study, we found that IL6/STAT3 pathway confers resistance to HOXC10 inhibition in KRAS-mutant lung cancer bone metastasis and that activation of p-STAT3Tyr705 further promotes cell survival after HOXC10 inhibition." (PMID 39191757, 2024). "IL-6 can further activate the EMT pathway in lung adenocarcinoma cells and promote metastasis, and the use of neutralizing antibodies against IL-6 can inhibit the metastasis of lung cancer in vitro and in vivo." (PMID 38424624, 2024). "Here, we demonstrated two important roles of IL-6 in cigarette smoke-promoted lung cancer osteolytic bone metastasis." (PMID 38993553, 2024). "IL-6 was found a robust correlation with lung cancer within the first year following diagnosis (OR = 2.56, 95% CI: 1.92–3.41)." (PMID 38339264, 2024). "Lung cancer patients have elevated levels of interleukin-6 (IL-6), which can upregulate hepcidin (a systemic iron availability regulator – for more information on iron homeostasis regulation, refer to our review titled “ Iron and Organismal Aging”)." (PMID 39246326, 2024). "Third, recent study has revealed that MMA also activated fibroblasts in the tumor microenvironment (TME) to secrete IL-6, driving cancer progression, drug resistance, and metastasis in breast and lung cancers." (PMID 38252148, 2024). "Different studies on lung cancer have found that inflammatory mediators are overexpressed, especially IL-6." (PMID 38474590, 2024). "The PI3K and Akt inhibitors abolished the cigarette smoke-mediated luciferase activity of NF-κB, indicating that the PI3K, Akt-activating NF-κB mediate cigarette smoke-induced promotion of IL-6 synthesis and cell motility in human lung cancer." (PMID 38993553, 2024). "Focusing on the insights into lung cancer, the production of IL-6 in lung TME actuates a signaling response in T-cells, M2 macrophages (TAM), and Type III immune cells, including CAFs and endothelial cells." (PMID 37893079, 2023). "Our study demonstrates the association between serum levels of IL-6, IL-1β, and IFN-γ and the lung cancer risk." (PMID 38067398, 2023). "Resveratrol has been demonstrated to suppress tumor activity in lung cancer, specifically by inhibiting lung cancer stem-like cell stemness and reducing IL-6 levels." (PMID 38136176, 2023). "Collectively, these findings indicate that TGFβ activates NF-kB through p38 MAPK in lung cancer cells, and SC-1 inhibits TGFβ-mediated IL-6 secretion via the p38–NF-kB signaling cascade." (PMID 37511415, 2023). "In K-ras mutant lung cancer mouse model, IL-6 was found overexpressed and blocking IL-6 with monoclonal antibody significantly reduced airway inflammation and dampened lung tumor cell proliferation and angiogenesis." (PMID 36986550, 2023). "We use αCSF1R (anti-CSF1R antibody), PLX3397, and αIL-6 (anti-IL-6 antibody) to treat subcutaneous lung cancer as method described." (PMID 36969873, 2023).
lung carcinoma (continued). "Fibroblasts, isolated from human lung cancer tissues, were found to actively secrete IL-6 and enhance metastatic activity in human lung cancer cell lines through JAK2 and STAT3 signal transduction activation." (PMID 36986550, 2023). "The results demonstrated that treatment of lung cancer A549 cells with LPS and ATP induced the expression of IL-6 and inflammasome-related cytokines IL-1β and IL-18, as well as increased NLRP3 gene expression." (PMID 38026959, 2023). "Early indications are that inflammatory cytokines such as IL-6 and IL-8 play a predictive role in lung cancer." (PMID 36874133, 2023). "The results showed that the levels of IL-6 in the blood were higher among patients with lung cancer than in patients with benign diseases." (PMID 37373987, 2023). "In line with previous studies, this investigation suggests the associations among serum levels of IL-6, IL-1β, and IFN-γ and the lung cancer risk, underscoring the potential of these cytokines to act as risk biomarkers." (PMID 38067398, 2023). "Apparently, DDIAS activates STAT3 and promotes migration and invasion by expressing genes such as survivin, slug, and vimentin in response to interleukin-6 (IL-6) in lung cancer cells." (PMID 37121974, 2023). "In lung carcinoma cells, macrophages secrete Il-6, which is responsible for inducing EMT by activating the cyclooxygenase 2 (COX2), prostaglandin E2 (PGE2), and beta-catenin signaling pathways." (PMID 38982997, 2023). "In an experiment of C3G plus 5-FU (a commonly used basic chemotherapy drug) in nude mice against lung cancer, the inflammatory cytokine, IL-1β, IL-6 and TNF-α, COX-2, NF-kpa and PCNA was decreased." (PMID 36771198, 2023). "This study shows associations between serum levels of IL-6, IL-1β, and IFN-γ and lung cancer risk, underscoring the potential of these cytokines to act as risk biomarkers." (PMID 38067398, 2023). "In a study led by Pine SR., it was shown that IL-6 in the serum had high levels in patients diagnosed with lung cancer." (PMID 37373987, 2023). "Our study highlights the significant role of IL-6 in the universal mechanism of lung cancer development." (PMID 38067398, 2023). "IL-6 facilitates epithelial to mesenchymal transition in lung cancer increasing vimentin expression, and in colorectal cancer via integrin β6 upregulation." (PMID 36982207, 2023). "Of which, IL-6 and IL-17 are known to induce the expression of autophagic intermediates that lead to macroautophagy in lung cancer." (PMID 37893079, 2023). "Several studies have shown that patients with lung cancer and elevated values of IL-6 in the serum have a worse prognosis." (PMID 37373987, 2023). "In lung cancer models, IL-6 promoted M2 polarization among macrophages, which led to elevated PD-1 mRNA expression in CD8+ T cells." (PMID 37958406, 2023). "Early work examining OSM in lung adenocarcinoma suggested it as a tumor promoter, including in vitro work showing OSM, and IL-6 to a lesser degree, as a potent inducer of human lung cancer differentiation." (PMID 37841259, 2023). "In lung cancer, some cytokines were significantly elevated in patients, such as interleukin-6 (IL-6), which has broad functions in regulating cancer cells." (PMID 36814297, 2023). "The correlation between the cancer progression with gender was studied in previous study, the correlations among IL‐6, D‐dimer, and PD‐1 efficacy in lung cancer patients of different genders were further investigated." (PMID 37326149, 2023). "Although serum interleukin 6 (IL-6) is a mediator of inflammatory diseases and lung cancer and indicates a worse prognosis, it unexpectedly promotes ferroptosis in bronchial epithelial cells." (PMID 37507867, 2023). "It was also noted that BAL fluid IL-6 was further elevated during radiotherapy, consistent with a previous observation that BALF TGF-b1 and IL-6 levels rise during RT for lung cancer." (PMID 37373957, 2023).
lung carcinoma (continued). "IL-1b and IL-6 are also markers for alveolar macrophage activity and can influence lung cancer survival prognosis." (PMID 37373957, 2023). "Consistently, lung cancer patients with high IL-6 expression displayed significantly shorter disease-free survival (DFS) and overall survival (OS) than those having lower IL-6 expression." (PMID 37696858, 2023). "The ROC plot analysis revealed that IL-1b, IL-2, IL-6, IL-10, IL-12p70, and TNF-alpha had a significant association with lung cancer, although with relatively low discriminative performance." (PMID 37373957, 2023). "Lowering pro-inflammatory cytokines, such as IL-1β, IL-2, IL-6, IL-8, IL-10, IL-12, interferon γ (IFN-γ), TNF-α, and granulocyte-macrophage colony-stimulating factor (CSF), can reduce lung cancer risk, particularly among smokers." (PMID 36986550, 2023). "Analysis of patient survival and relevant factors in lung cancer and pan-cancer cohorts supports the prognostic and clinical values of Panx1 and IL-6." (PMID 37696858, 2023). "On the other hand, miR-146b-5p has an inhibitory effect on IL-6 and IL-8, which are NF-κB regulated chemokines, in lung cancer cells." (PMID 36800962, 2023). "Lung cancer is also caused by chronic inflammation, and many pro-inflammatory genes, including TNF-α and IL-6, are crucial for apoptosis, proliferation, angiogenesis, and metastasis inhibition." (PMID 37894468, 2023). "Further examination of the correlations among IL‐6, D‐dimer, and PD‐1 efficacy in lung cancer patients stratified by gender revealed a significant association of IL‐6 levels with risk of PFS in male but not female patients." (PMID 37326149, 2023). "Several interleukins, including IL-1 beta, IL-6, and IL-8, have been identified to be dysregulated in lung cancer." (PMID 37760616, 2023). "Studies have shown that WNT5A regulates IL-6 expression in melanoma and modulates the expression of SASP factors in tendon stem cells, and that IL-6 exhibits a reciprocal regulation with CCL2 in non–small cell lung cancer." (PMID 37607007, 2023). "High IL-6 expression correlates positively with poor survival outcomes in melanoma, head and neck cancers and lung cancers." (PMID 35655772, 2022). "Meanwhile, ectopic expression of P65 also rescued S phase blockage and expression of cell cycle-related genes including CDK2, Cyclin D1 and Cyclin E1, in addition to NF-κB target genes including IL-1β, IL-6 and TNFα in lung cancer cells overexpressing ZNF24." (PMID 36457047, 2022). "In a prospective study, patients who underwent lung cancer surgery with thoracic epidural anesthesia had significantly lower IL-6 levels in serum and lung epithelial lining fluid." (PMID 35898583, 2022). "In this study, we explored the novel role of MRE11 in the IL6/STAT3/CCL2 signaling pathway in lung cancer." (PMID 36547079, 2022). "We began the analysis by examining the effect of independent variables (subtype and stage of lung cancer, etc.), on the levels of hepcidin, IL-6, and TNF-α." (PMID 36612220, 2022). "In lung cancer, activation of Akt1/IL‐6/STAT3 pathway also contributes to maintaining the stemness of tumour initiating cells." (PMID 34997691, 2022). "Our data support the role of hepcidin, IL-6, and TNF-α in cancer-related anaemia and provide diagnostic values for predicting post-operative anaemia in lung cancer patients." (PMID 36612220, 2022). "Especially since we can predict which operative lung cancer patients will develop anaemia during hospitalization using hepcidin, IL-6, and CRP testing and include these patients in anaemia prevention treatment." (PMID 36612220, 2022). "In sharp contrast, S1P significantly increased the levels of TNF-α and IL-6 from lung cancer-derived PBMCs." (PMID 36010601, 2022). "Interleukin (IL)-6 is one of the most typical tumor-promoting cytokines, which can promote the migration and invasion of lung cancer and angiogenesis, and can promote the metastasis of NSCLC through the IL-6-STAT3 pathway." (PMID 36157452, 2022).
lung carcinoma (continued). "This study retrospectively analyzed the level of serum CEA, IL-1β, IL-6, and IL-8 in patients with lung cancer, and the relationship between levels of these ILs with the pathological type and clinical stage of patients with lung cancer." (PMID 35928100, 2022). "IL-6 has been shown to exhibit increased production in various cancer types, including breast cancer, colorectal cancer, and lung cancer." (PMID 35928100, 2022). "Elevated IL6/ERβ expression in lung cancer was seen to be correlated to less differentiation and increased metastasis, and the expression of IL6 was suggested to be an independent predictive factor for overall survival (OS)." (PMID 35631448, 2022). "In lung carcinoma Lewis will upregulate IL-1β and IL-6 through the p38/mitogen activated protein kinase (MAPK) pathway." (PMID 35340325, 2022). "NF-­κB activation is rapidly induced in response to EGFR oncogene inhibition in lung cancer and promotes resistance to therapy via interleukin 6 (IL­-6) induction." (PMID 35399416, 2022). "In this study, we found that the levels of CEA, IL-1β, IL-6, and IL-8 in the lung cancer group were significantly higher than those in the healthy group, consistent with the reports in the literature." (PMID 35928100, 2022). "IL-6/STAT3 signaling has been associated with tumor progression in BC and lung cancer by inducing EMT and angiogenesis." (PMID 35626741, 2022). "As indicated in another study conducted in lung cancer, patients with high circulating IL-6 levels have significantly more T-regulatory cells and increased programmed cell death protein-1 expression on lymphocytes." (PMID 36153540, 2022). "Two of the genes identified in our study were ROS1, which is widely studied in the treatment of lung cancer, and IL-6, which plays a role in tumor microenvironment changes." (PMID 35529255, 2022). "In the study, it was also found that IL-6 and IL-8 levels are increased many years before the diagnosis of lung cancer." (PMID 36140220, 2022). "We supplemented our findings with a statistical analysis of the diagnostic value of hepcidin, IL-6, TNF-a, CRP, and SAA1 in the examination and differentiation of anaemia in lung cancer patients." (PMID 36612220, 2022). "Lung cancer patients also showed increased concentrations of serum IL-9, IL-6, and enhanced arginase activity." (PMID 35778404, 2022). "Blocking IL-6 expression can inhibit lung cancer promotion, cell proliferation, angiogenesis markers, and tumor cell-intrinsic STAT3 activation." (PMID 36437827, 2022). "In contrast, lung cancer patients with CIP, shown to have increased IL-6, were associated with the occurrence of disease." (PMID 35558076, 2022). "In lung cancer, IL6 was involved in cell autonomous propensity for metastasis and establishing the metastatic niche." (PMID 35692583, 2022). "One study suggests that STAT3-regulated CD5 expression on B cells drives IL-6 signaling and disease progression in lung cancer." (PMID 35406557, 2022). "The pharmacological blockade of ceramidase and sphingosine kinases (SPHKs), key enzymes for S1P synthesis, completely reduced the release of both TNF-α and IL-6 after S1P addition on lung cancer-derived PBMCs." (PMID 36010601, 2022). "IL6 is one of the commonly expressed genes by both human and mouse TAMs, and macrophages are the major IL6 expressing population in lung cancer patients." (PMID 35778404, 2022). "ERO1L and XBP1 can activate IL-6 pathway and promote the progression of lung cancer and HCC, respectively." (PMID 35805045, 2022). "In the IL family, IL-1β, IL-6, and IL-8 are cytokines with a wide range of biological activities, which are involved in the occurrence and metastasis of many kinds of tumors, lung cancer is one of them." (PMID 35928100, 2022). "HMA inhibits the growth of A549 lung cancer cells, which is related to the induction of apoptosis and inactivation of IL-6/JAK2/STAT3 signaling pathway." (PMID 36591515, 2022).